IL18 (interleukin 18)
Diseases named in the same sentence as IL18 in open-access papers (continued):
Sharing a sentence is not in itself a finding about the gene and the disease.
chronic kidney disease (34 papers, 2008 to 2026). Impairment of the renal function secondary to chronic kidney damage persisting for three or more months. "Inflammation underlies the pathogenesis of many acute or chronic kidney diseases, and IL-18 plays an important role." (PMID 33732720, 2021). "This is supported by experimental data showing that inflammasome-regulated cytokines such as IL-1β and IL-18 are implicated in animal models of chronic kidney disease, including glomerulonephritis and renal ischemic injury." (PMID 23843683, 2013). "In some studies, elevated level of IL-18 was paired with increase in TNF-alpha in chronic kidney disease." (PMID 36558477, 2022). "The serum levels of interleukin (IL) 1β (17.5 kDa), IL-6 (21.0–28.0 kDa), and IL-18 (18.0 kDa) as well as κ (22.5 kDa) and λ (45.0 kDa) free light chains (FLCs) are also elevated in patients with advanced chronic kidney disease (CKD)." (PMID 31892319, 2019). "Interleukin-18 binding protein is a natural inhibitor of IL-18, which is involved in immunosuppression in chronic kidney disease through the reduction of excretion." (PMID 26496326, 2015). "In humans, IL-18 and caspase-1 are expressed in renal tubular epithelium, and patients with chronic kidney disease or the nephrotic syndrome exhibit elevated levels of IL-18." (PMID 23843683, 2013). "Consequently, renal inflammation is attenuated, as indicated by lower IL-1β and IL-18 concentrations, ultimately leading to improved renal function in rats with chronic kidney disease, as reflected by a significant reduction in Scr, BUN levels, and ACR." (PMID 40822454, 2025). "The urinary IL-18 level in patients with acute tubular necrosis has been shown to be significantly elevated compared to patients with urinary tract infections, pre-renal acute renal failure, chronic kidney disease, and nephrotic syndrome." (PMID 33732720, 2021). "Increased serum IL-18 levels in patients with chronic kidney disease and the correlation of urine IL-18 levels with disease activity in nephrotic syndrome indicates that pro-inflammatory cytokines may play a role in chronic kidney disease." (PMID 30876398, 2019). "Cross-sectional studies indicate that urinary IL-18 levels are markedly elevated in patients with acute tubular necrosis compared with healthy controls and a variety of other renal pathologies, including urinary tract infection, chronic renal insufficiency, and pre-renal azotemia." (PMID 24899123, 2015). "The chronic kidney disease group exhibited elevated serum urea and creatinine and reduced eGFR, along with increased levels of KIM-1, NGAL, IL-18, TNF-α, IL-6, NF-κB, and FMO3." (PMID 40978750, 2025). "In this regard, a larger study based on the PRESERVE trial cohort was conducted, measuring plasma biomarkers in 916 patients and urine biomarkers in 797 patients with chronic kidney disease: MCP-1, KIM-1, NGAL, IL-18, UMOD, and YKL-40 in 19 different centers." (PMID 38254682, 2024). "Urine IL-18 concentrations have been found to be significantly raised in patients with AKI compared to those with urinary tract infection, chronic renal insufficiency and nephrotic syndrome." (PMID 32487191, 2020). "Urinary IL-18 levels are elevated in patients with AKI and delayed graft function compared to normal subjects and patients with prerenal azotemia, chronic renal insufficiency, and nephrotic syndrome." (PMID 28624882, 2018). "IL-18 has been shown to be more elevated in patients with established acute tubular necrosis AKI than in those with prerenal azotemia, urinary tract infection, or chronic kidney disease (CKD)." (PMID 28624882, 2018). "The widespread study of renal tubular injury biomarkers including KIM-1, NGAL, IL-18 and L-FABP as potential biomarkers for acute and chronic kidney disease has resulted in concerns about the impact of sample handling, processing and storage conditions on biomarker levels." (PMID 27788160, 2016).
chronic kidney disease (continued). "Furthermore, the concentrations of NGAL, KIM-1, IL-18 and L-FABP are higher in patients with chronic kidney disease than healthy controls, which might interfere in the differentiation between AKI and chronic kidney disease." (PMID 28107490, 2017). "Last but not least, we chose to assess IL-18 levels, as IL-18 is a part of NRLP3 inflammasome, whose role is currently gaining attention in the development of chronic kidney disease and its complications." (PMID 36558477, 2022). "NLRP3, IL-1β, and IL-18 are significantly upregulated in chronic kidney disease patients undergoing hemodialysis treatment, indicating that the NLRP3 inflammasome may be activated in and contribute to chronic inflammation in CKD." (PMID 32660446, 2020). "IL-18 is more specific to ischemic AKI and is not affected by nephrotoxins, chronic kidney disease, or urinary tract infections." (PMID 17394022, 2008). "In a cross-sectional study, urine IL-18 levels were markedly increased in patients with established AKI but not in subjects with urinary tract infection, chronic kidney disease, nephritic syndrome, or prerenal failure." (PMID 17394022, 2008).
dengue (34 papers, 2010 to 2025). "The earlier study from children, suggests that more elevated ferritin and IL-18 are associated with the severe dengue." (PMID 36091089, 2022). "Simultaneously, caspase activation also cleavage the pro-IL-1β and pro-IL-18 to their active form, causing the inflammatory cascade to be activated and promoting further advances in dengue pathogenesis." (PMID 34840991, 2021). "The triggering of severe dengue has been associated with an exacerbated inflammatory process characterized by the production of pro-inflammatory cytokines such as IL-1β/IL-18, which are the product of inflammasome activation." (PMID 30901375, 2019). "Our data demonstrated that free circulating IL-18 was associated with severity of the dengue disease." (PMID 28569153, 2017). "Here we observed that the severity of dengue disease was associated with aberrant activation of monocyte or macrophages as evidenced by elevation of plasma IL-18, sCD14 and LBP particularly at the febrile phase." (PMID 28569153, 2017). "Recent studies further demonstrates that serum IL-1β and IL-18 levels correlate with susceptibility to dengue." (PMID 23742038, 2013). "Our multivariate model showed that all the three IL-18, LBP and sCD14 markers at febrile phase were independently associated with the more severe form of dengue disease; whilst at defervescence phase, only was IL-18 was found to be independently associated with severity of dengue disease." (PMID 28569153, 2017). "The cytokines IL-17 and IL-18, in particular, seem to be widely expressed in the kidney during severe cases of dengue." (PMID 37162062, 2023). "We also determined the bioavailability of IL-18, and found that the plasma levels of IL-18 was significantly higher in patients with severe dengue followed by those with dengue with warning signs as well as dengue without warning signs." (PMID 35874775, 2022). "IFN-γ production dependent on IL-12 and IL-18 has also been observed in other infection models, as well as dengue virus infection." (PMID 34951583, 2021). "In agreement with our previous studies, another pro-inflammatory cytokine that increased markedly in the dengue patients in our study was IL-18." (PMID 34578370, 2021). "A previous report showed a similar result, where IL-18 significantly increases in severe dengue compared to the healthy samples of patients with mild dengue infection." (PMID 34734091, 2021). "High serum IL-18 is remarkably correlated with severely ill dengue patients; however, its possible roles have been less explored." (PMID 34840991, 2021). "In our study, it was shown that the transaminase levels of the dengue patients had positive correlations with the plasma levels of IL-18." (PMID 34578370, 2021). "Dengue virus mediated inflammasome initiates the maturation of IL-1β and IL-18, which are critical for dengue pathology and inflammatory response." (PMID 33014899, 2020). "For example, interferon gamma (IFN-γ), interleukin 12 (IL-12) and interleukin 18 (IL-18) are essential for an effective host immune response against dengue virus infection." (PMID 28644404, 2017). "To gain better insight into the regulation of biological activity of IL-18 during dengue disease, we measured the plasma levels of IL-18BPa and free circulating IL-18 levels were estimated." (PMID 28569153, 2017). "Activation of MAIT cells in acute dengue correlated both with disease outcome and with IL-18 signals." (PMID 27337592, 2016). "Previous research has shown that some of the cytokines and chemokines released during dengue fever, including Il-6, IL-8 and IL-18, are also seen in preterm delivery." (PMID 25299383, 2014). "Levels of ferritin, standard laboratory markers, sIL-2R, IL-18 and coagulation and fibrinolytic markers were determined in samples from patients with uncomplicated dengue in Aruba." (PMID 25299654, 2014).
dengue (continued). "IFN-γ production upon infection is controlled by concomitant production of IL-12 and IL-18 and the IFN-γ-dependent mechanisms associated to resistance to dengue disease involve NOS2 up-regulation and consequent NO production." (PMID 22206036, 2011). "This suggests that the cytokine storm occurring in severe dengue disease may be due to inadequate regulation of IL-18 responses by IL-18BP." (PMID 35874775, 2022). "It was demonstrated that the IL-18 level was higher in dengue than in control." (PMID 34840991, 2021). "Finally, we discovered that IL-18 levels were significantly higher in the various group circumstances, making it a plausible option for a dengue severity measure, particularly when severe with comorbid groups." (PMID 34734091, 2021). "Moreover, a decrease in the expression of the inflammasome-related genes NLRP1, NLRC4, caspase-1, IL-1β and IL-18 was observed, as well as an increase in serum levels of C-reactive protein and IL-10 in dengue patients versus healthy donors." (PMID 30901375, 2019). "Having showed that plasma levels of IL-18 was associated with the severity of dengue disease, we next assessed the circulating levels of this regulatory molecule and the free circulating IL-18 (fraction of IL-18 that do not bound to IL-18BP)." (PMID 28569153, 2017). "Our results show that the elevation of plasma levels of IL-18 at both febrile and defervescence phase was significantly associated with DWS+ and SD; whilst increase of sCD14 and LBP at febrile phase were associated with severity of dengue disease." (PMID 28569153, 2017). "Given that the elevation IL-18, LBP and sCD14 among patients with severe form of dengue disease, our findings suggest a pathogenic role for an aberrant inflammasome and monocyte activation in the development of severe form of dengue disease." (PMID 28569153, 2017). "Furthermore, the free circulating IL-18 remained significantly elevated among patients with the more severe form of dengue disease." (PMID 28569153, 2017). "In addition, patients suffering from the severe form of dengue (DHF) had significantly higher levels of IL-18 over the course of acute infection compared to patient with DF." (PMID 27337592, 2016). "Elevated levels of IL-18 and IL-18BP have been observed in patients with idiopathic thrombocytopenia purpura, suggesting a possible link to reduced platelet number and/or function, as in severe dengue and leptospirosis." (PMID 24444080, 2014). "IL-18 serum level correlates with thrombocytopenia and dengue hemorrhage." (PMID 23742038, 2013). "Moreover, circulating IL-18 and ferritin levels may strongly correlate with dengue disease severity and can be considered a tool for predicting disease progression." (PMID 39273479, 2024). "In the case of dengue, the local elevation of GM-CSF triggers inflammatory macrophages, where DENV replicates efficiently and activates the NLPR3 inflammasome through CLEC5A to induce the massive production of IL-1β and IL-18, which are proinflammatory cytokines associated with severe dengue." (PMID 36297236, 2022). "The first report about an IL-18 increase in a dengue patient clinical study was published in 2001, where the results from serum examination showed high IL-13 and IL-18 in the severe illness and late dengue disease phase (over 9 days from disease onset) patients." (PMID 34840991, 2021). "Here, we presented the main pathway associated with Dengue disease (immune response—role of protein kinase regulated by double-stranded RNA (PKR) in stress-induced antiviral cell response) and with liver failure (immune response—Interleukin-18 (IL-18) signaling)." (PMID 33182673, 2020). "However, the IL-18 levels were similar in individuals with dengue versus healthy controls." (PMID 30901375, 2019). "Hence, it is likely that the combination of increased IL-18 levels and decreased IL-12 levels may also play an important role in dengue immunopathogenesis." (PMID 31009499, 2019).
dengue (continued). "It is, however, important to note that elevated levels of circulating IL-18 in dengue virus infections concur with increased levels of the antagonistic IL-18 binding protein (IL-18BP), resulting in unchanged plasma concentrations of free, biologically active IL-18." (PMID 27977798, 2016). "Moreover, circulating levels of both IL-18 and ferritin show strong correlation with dengue disease severity and, therefore, may be considered as a tool to predict disease progression." (PMID 27977798, 2016). "We measured and compared the levels of IL-18 and CXCL-10 with the different severity levels of Dengue." (PMID 41227147, 2025). "Further studies should explore the mechanistic role of IL-18 and CXCL10 in Dengue pathogenesis and their potential as therapeutic targets for managing severe cases of the disease." (PMID 41227147, 2025). "Therefore, the use of IL-18 could predict early disease progression to more severe Dengue." (PMID 41227147, 2025). "Among them, a vast panel of increased cytokines and chemokines in severe dengue, such as IFN-γ, GM-CSF, IL-10, CCL4/MIP-1β, IL-1β, CXCL8/IL-8 TNF-α, CXCL10/IP-10, CCL2/MCP-1, and IL-18." (PMID 35631030, 2022). "Previous studies shown that abnormal inflammasome and monocyte activation play a pathogenic role in the development of dengue, supported by evidence based on clinical samples in which IL-18, LBP and sCD14 are elevated in patients with severe dengue." (PMID 36091000, 2022). "In dengue MAIT cell activation – measured by CD38 expression – peaked at the day of defervescence, and correlated with more severe disease and with plasma IL-18." (PMID 35381137, 2021). "In our study, higher plasma levels of the proinflammatory cytokines TNF-α, IL-6 and IL-18, and the anti-inflammatory cytokine IL-10 and the chemokines CXCL8/IL-8, CCL2/MCP-1 and CXCL10/IP-10 were found in the dengue patients compared to the healthy controls." (PMID 34578370, 2021). "IL-18 is a cytokine secreted from activated monocytes/macrophages and can induce IFN-γ secretion in severe dengue." (PMID 34734091, 2021). "Based on the clinical and basic findings, this review discusses the potential immunopathogenic role of IL-18 when it participates in DENV infection and dengue disease progression based on existing findings and related past studies." (PMID 34840991, 2021). "IFN-γ, IL-10 and IL-18 have been frequently reported to be higher in the serum of DHF/DSS patients compared to DF patients and may thus be considered as immune markers of severe dengue in humans." (PMID 31009499, 2019). "The next step was to quantify the serum levels of IL-1β, IL-6, IL-18, IL-10, TNF-α and CRP, as indicators of the inflammatory status in the dengue patients." (PMID 30901375, 2019). "Further ROC analysis revealed that the cut-off values for distinguishing severe Dengue from non-severe Dengue for IL-18 and CXCL-10 were both 669.65 pg/mL, whereas that of CXCL-10 was 3739.5 pg/mL." (PMID 41227147, 2025). "Blood samples of patients with Dengue were only collected at a time point of admission for measuring of IL-18 and CXCL-10; therefore, we did not monitor dynamic changes in IL-18 and CXCL-10 levels during the course of the disease." (PMID 41227147, 2025). "Furthermore, based on the analysis of ROC curves, we determined the cut-off values of IL-18 and CXCL-10 for predicting Dengue severity." (PMID 41227147, 2025). "In a previous study, we compared the plasma level of IL-18 and IL-18BP among dengue patients with and without warning signs as well as severe dengue." (PMID 35874775, 2022). "IL-1β, IL-18, IL-33 and high-mobility group B1 (HMGB1) represent the key inflammatory mediators produced during hypercytokinemia, via the inflammasome pathway and have been shown to correlate with dengue severity." (PMID 35874775, 2022). "Having said that, the bioavailability of IL-18 is higher among patients with severe dengue as well as among those with warning signs as compared to dengue without warning signs." (PMID 35874775, 2022).
dengue (continued). "In addition, our study found a positive association between APRI values and the levels of pro-inflammatory cytokines, chemokines and coagulation mediators (IL-6, IL-18, CXCL10/IP-10 and TFPI) in dengue patients." (PMID 34578370, 2021). "As in our previous studies, the dengue patients had high plasma levels of the cytokines TNF-α (p < 0.001), IL-6 (p = 0.005), IL-10 (p < 0.001) and, IL-18 (p = 0.001) and the chemokines CXCL8/IL-8 (p < 0.001), CCL2/MCP-1 (p < 0.001), CXCL10/IP-10 (p = 0.001) compared to healthy controls." (PMID 34578370, 2021). "Therefore, increased IL-18 and IL-8, probable increased IL-6 and TNF-α together with decreased IFN-γ and RANTES in acute SDD patients resemble cytokine involvement in severe dengue progression." (PMID 34734091, 2021). "The elevation of IL-18 among DWS+ and SD patients in this cohort suggest that aberrant activation of the inflammasome may play a role in dengue immunopathogenesis, consistent with previous reports." (PMID 28569153, 2017). "By using receiver operating characteristic (ROC) analysis, the IL-18, LBP and sCD14 were significantly predicted the development of more severe form of dengue disease (DWS+/SD) (AUC = 0.768, P < 0.0001; AUC = 0.819, P < 0.0001 and AUC = 0.647, P = 0.014 respectively)." (PMID 28569153, 2017). "In the dengue virus infection, peripheral blood NK cells showed CLA and other homing receptors (CCR5 and CXCR6) increased expression, in a pathway related to augmented plasmatic IL-18 levels, indicating an IL-18-dependent mechanism inducing NK cell proliferative response." (PMID 38302650, 2024).